E2F1 (E2F transcription factor 1)
Diseases named in the same sentence as E2F1 in open-access papers (continued):
Sharing a sentence is not in itself a finding about the gene and the disease.
cancer (continued). "Such a set of hubs contained important transcription factors such as MYC and E2F1 and oncogenes such as JUN and RELA and was enriched with genes that appeared in cancer pathways (p<2.2×10−8), the cell cycle (p<3.5×10−6) and several important signaling pathways from DAVID." (PMID 21390271, 2011). "Other cancer-related genes located within this SRO include PIGU, E2F1, and DNMT3B." (PMID 19486517, 2009). "The increase is moderate in cancer cells, such as SaOs cells, whereas it is highly efficient in noncancer cells, for example in the IMR90 cell line, probably due to the fact that ICBP90 is already expressed at a high level before E2F-1 overexpression." (PMID 12838312, 2003). "Moreover, all 33 cancer cell lines tested possessed distinct E2F1 activity, while the five normal growing cell types did not." (PMID 41511373, 2026). "Therefore, the lactate-induced E2F1 activation, with its downstream regulation of KIF20A, contributes to the carcinogenic cascade, fostering the migration and metastasis of cancer cells and delineating a lactate-E2F1-KIF20A pathway integral to cancer progression." (PMID 39272816, 2024). "A pan-cancer study indicated that KAT2A was found to cooperate with E2F1 and be recruited by E2F1 to the UBE2C promoter for elevating the expression of UBE2C by increasing the acetylation level of H3K9 to promote cell proliferation and the migration of cancer cells." (PMID 39546499, 2024). "However, Akt is an upstream factor of c-Myc and E2F1, and it is not clear how SET-induced Akt activation benefits cancer cells without affecting protein levels of c-Myc and E2F1." (PMID 38141761, 2024). "Furthermore, E2F1 also activated DANCR transcription, forming an E2F1/DANCR/miR-34c-5p positive feedback loop, presenting novel approaches for tackling cancer progression." (PMID 39119602, 2024). "Thus, deregulated E2F1 activity, which activates the ARF gene, exists specifically in cancer cells." (PMID 39595534, 2024). "Overexpression of HDAC1 or E2F1 partially reversed the inhibitory effect of HR488B on cell viability and the co-expression of HDAC1 and E2F1 was more effective to reverse the inhibitory effect of HR488B, which confirmed that HR488B executed its anti-cancer effect via the HDAC1-E2F1 axis." (PMID 38062013, 2023). "Finally, we silenced E2F1 in different normal and cancer cell lines of both sexes and no significant changes in TSPYL2 mRNA levels were found in unstressed conditions." (PMID 36918555, 2023). "In order to verify the prognosis of E2F1 for cancer, we searched in the online databases GEPIA, which contains survival and differential expression analyses of genes and in Kaplan–Meier Plotter database, which includes the effect of genes, protein on survival in 21 cancer types." (PMID 37277745, 2023).
cancer (continued). "To examine whether human lncRNA genes behave in a similar way to that observed in murine cancer cells and further investigate the effect of PRMT5 and E2F1, we explored lncRNA expression upon PRMT5 inhibition and CRISPR knock-out (KO) of the E2F1 gene in HCT116 cells derived from human CRC11." (PMID 36841868, 2023). "Therefore, we found that PRR11 served as an oncogene in pan-cancer and could influence the cell cycle progression through regulating the expression of PTTG1 by interacting with the transcription factor E2F1." (PMID 36060253, 2022). "In the group of cancer patients, we found a significantly higher portion of women (4.5%, 10/222) with more than two copies of E2F1, compared with controls where none of subjects harboured E2F1 CNVs > 2 (0%, 0/200; p = 0.002)." (PMID 33691613, 2021). "Moreover, we show that PLANE is frequently upregulated in diverse cancer types through genomic amplification and E2F1-mediated transcriptional activation, with practical implications of interference with PLANE as potential treatment approach in the pan-cancer context." (PMID 34145290, 2021). "Likewise, BTYNB decreased E2F1 expression and vitality of all other here investigated cancer cell lines without affecting IGF2BP1 abundance." (PMID 32761127, 2020). "The induction of E2F1 requires PI3Kδ and inhibitors of PI3Kδ (Idelalisib) have been tested in the clinic for non-EBV related cancers and it might be worth considering using PI3Kδ inhibitors against EBV-carrying cancers." (PMID 32453417, 2020). "However, in luminal B cancers, where the amplicon is more often present, E2F1 programs, dependent on CDK4/cyclin D activation, may substitute for ER programs, which have lower activity in these cancers." (PMID 32987805, 2020). "We identified 28 gene sets and 95 core genes exacerbated in the C2 class, and two transcription factors (E2F1 and FOXM1) that are known to affect prognosis and response to therapy in different cancer types, and might be responsible for most of the differences between the two classes." (PMID 33396205, 2020). "However, the reason for high-level E2F1 expression in human cancer cells and the specific role of E2F1 in maintaining genomic integrity in cancerous cells are not clearly understood." (PMID 31534120, 2019). "Accumulating evidence shows that NCOA3 is highly expressed in a various human cancers, and it can interact with nuclear receptors and other transcription factors to regulate the expression of their target genes involved in many signaling pathways, including EGFR, Akt, MAPK, E2F1, and Notch." (PMID 29360267, 2018). "In addition to E2F1, several known potent oncogenes regulate ANRIL expression in various cancers." (PMID 30087655, 2018). "Specifically, E2F1 expression levels could be used to discriminate the cancer tissues from non-tumorous tissues." (PMID 28569791, 2017). "In addition to the inflammation pathway, several cancer-related pathways were identified from the global NSAIDs-regulating miRNA-gene subnetwork, including cell cycle (CDK6, CCND1, CCKN1A, and E2F1), proliferation (MYC), apoptosis (BCL2) and angiogenesis (VEGFA)." (PMID 27329603, 2016). "Using a panel of human cancer cell lines of different origins, we found that E2f1 co-precipitated with Pontin in several lines, indicating that recruitment of homo- or hetero-Pontin/Reptin complexes by E2f1 is a common, albeit not ubiquitous, phenomenon in cancer." (PMID 26639898, 2015).
cancer (continued). "Ad5/3-E2F-Δ24-GMCSF achieved cancer cell killing efficacy comparable to the isogenic control without the E2F1 promoter and wild type Ad5, while being superior to the non-replicative Ad5/3luc1 (P < 0.05), which implies retained oncolytic potency despite quadruple genetic modification." (PMID 25714011, 2015). "Since E2F1 conferred resistance to genotoxic insults, we further investigated whether elevated DSCC1 expression plays a role in the sensitivity of cancer cells to genotoxic stimuli." (PMID 24465681, 2014). "Interestingly, a recent study has shown that human HMGA1 promoter is target of E2F1 and the deregulated RB1/E2F1 pathway might contribute to deregulation of HMGA1 in cancer." (PMID 25364713, 2014). "However if there is no expression of ERα, Bmi1 may be induced by other factors such as E2F1 and MYC, both of which are usually expressed in cancers." (PMID 24559156, 2014). "However, strong evidence for the functional interaction between DDB2 and E2F1, a proliferative marker in many cancers led us to speculate that DDB2 could be involved also in cancer cell growth." (PMID 18431487, 2008). "Furthermore, since p21 is dysregulated in some tumors, it could be interesting to further investigate the action of dex on the multicomplex protein assembly Lamin A/C, HDAC2, LAP2α, pRb, E2F1, and FoxO3a on the CDKN1A promoter that might regulate p21 expression, in some cancer cell types." (PMID 37345209, 2023). "Besides, based on GENPIA, E2F1 and CKS2 had significantly positive co-expression in 21 of 33 types of cancer, which might be a possible reason why CKS2 always frequently elevated in many cancers." (PMID 36096885, 2022). "In addition, E2F1 and MAP2 are suggested as molecular targets for UVB first line of response that could be used to monitor proteins altered in genotoxic stress and/or molecular targets in cancer." (PMID 34068980, 2021). "They found that cancer cells without E2F1 could not copy their damaged DNA, and self-destructed." (PMID 31534120, 2019). "However, whether PUMA contributes to E2F-1-induced cancer cell apoptosis has not been fully elucidated." (PMID 17263886, 2007). "In addition, it has yet to be elucidated whether the dysfunction of the pathway upstream of pRB generates distinct E2F1 activity, and the extent to which distinct E2F1 activity is present or absent in a variety of cancer cell lines and normal growing cells has not been extensively investigated." (PMID 41511373, 2026). "After DNA damage, E2F1 promotes TSPYL2 gene expression in cells of both sexes, but the protein accumulates only in female cancer cells, where it is no longer ubiquitinated." (PMID 36918555, 2023). "E2F1 and E2F2 are highly expressed in many cancer types, but their contribution to malignancy is not well understood." (PMID 36230876, 2022). "Of note, four of the cancer genes present in the network (MAP2K2, E2F1, FZD2, and WNT7B), although absent from our high-confident list of CIRBP targets, are enriched in CIRBP IPs." (PMID 33172965, 2021). "The effect of overexpression of E2F-1 is more efficient on ICBP90 and TopoIIα expression in noncancer cells (IMR90, WI38) than in cancer cells (U2OS, SaOs)." (PMID 12838312, 2003). "We found that KLF5 did not affect E2F1 expression, and therefore, we suggest that KLF5 may play a part in promoting cancer by inactivating RB1 by regulating the expression of Cyclin D 1 and XPO1." (PMID 39888288, 2025).
cancer (continued). "Notably, along with our study, we found that expression of p-RPS6, E2F1, FOXM1, and WEE1 protein was elevated significantly in de-differentiated LPS cancer cells, relative to nonmalignant ASC52telo cells." (PMID 33564073, 2021). "E2F1 and NF-κB proteins are often deregulated in cancer and could account for the lack of FMN2 expression observed in certain cancer types." (PMID 23375502, 2013). "Also, these results show that the efficiency of the E2F-1 overexpression on the ICBP90 and TopoIIα expression is higher in noncancer cell lines (IMR90 and WI38 cells) than in cancer cell lines (SaOs and U2OS)." (PMID 12838312, 2003). "Conflicting reports of whether TNFα-induced RELA translocation is cell cycle regulated may be due to cancer cell type-specific deregulation of cell cycle proteins or RELA may not physically interact with E2F1 in PDAC cells in general or specifically in unsynchronised cells." (PMID 39110005, 2024).
infection (47 papers, 2007 to 2025). The state of being infected such as from the introduction of a foreign agent such as serum, vaccine, antigenic substance or organism. "Furthermore, E2F1 downregulation and the associated microRNA alterations promote Salmonella replication within infected cells and prime bystander cells for more efficient infection." (PMID 34099666, 2021). "Infection of Saos-2 cells with E2F1-expressing virus at MOI of 2, which is far lower than that used for HFFs (MOI of 20), induced significant cell death, about 35%." (PMID 39769018, 2024). "The genes specifically downregulated over the course of infection by Fasciola miRNAs included Nod1, E2f1, Tnfaip3 and Cdk6 at 6 hrs, and Jam3, Vegfa, Nod1, Uvrag and Nlrc3 at 18 hrs." (PMID 39344634, 2024). "To obtain a similar amount of protein expression, we titrated the multiplicities of infection (MOI) of E2F1- and ∆NE2F1-expressing viruses in both HFFs and U-2 OS cells and examined expression levels by Western blot analysis." (PMID 39595534, 2024). "One important finding of the described combination therapy with CDK4/6i and XVir-N-31 is the observation that RB expression remains downregulated throughout viral life cycle in the combination therapy whereas E2F1 level recover already 12 h past infection." (PMID 35948546, 2022). "Expression of the E2F1 gene was increased by BKPyV-infection (p < 0.001) along with other members of the E2F family." (PMID 35194151, 2022). "Here, we analyzed the role of the transcription factor E2F1 in the regulation of miRNAs upon infection with the bacterial pathogen Salmonellaenterica serovar Typhimurium (hereafter, Salmonella)." (PMID 34099666, 2021). "Here, we demonstrate that the activation of the ER-stress response, and consequent E2F1 and miRNA downregulation, is beneficial for Salmonella replication and dissemination of infection." (PMID 34099666, 2021). "This analysis revealed that E2F1 protein levels are decreased at 4 hpi, gradually lowering with the progression of infection (8 and 20 hpi)." (PMID 34099666, 2021). "Interestingly, ER-stress response was only triggered by infection or treatment with the secretome of invasive Salmonella strains (WT and ΔSPI-2), but not with the non-invasive strain ΔSPI-1, suggesting a causal relationship between ER-stress response and E2F1/miRNA regulation." (PMID 34099666, 2021). "Adenoviral E1A expression was increased at 24–48 h, and expression of the downstream mediator E2F1 was increased at 48–72 h after infection with OBP-301 or OBP-702." (PMID 32637577, 2020). "To examine the effect of DP1 knockdown on E2F-mediated apoptosis, we measured the percentage of cells with a sub-G1 DNA content and that stained with annexin V by flow cytometry at 72 h after infection of WI-38 cells with Ad-E2F1 or Ad-12SE1A." (PMID 29855511, 2018). "Infection with the E2F1 expressing virus increased E2F1 protein and, as expected, the mRNA levels of the known E2F responsive genes, Cyclin E and PCNA." (PMID 28228757, 2017). "Infection with EBVGFPΔ130-159 virus also increased E2F1 protein, especially at 2 and 5 dpi (1.2 and 1.25 fold change respectively), but the levels were down regulated at 7 dpi (1.00 fold) consistent with the mRNA levels determined by qRT-PCR." (PMID 26908453, 2016). "To support the gene expression profiles obtained with qRT-PCR, we also determined the protein levels of E2F1 in PBMCs infections." (PMID 26908453, 2016). "In order to determine a definitive role for residues 130-159 of EBNA3C in attenuating this E2F1 mediated DNA damage response, we infected PBMCs with EBVGFPΔE3C130-159 virus to analyze E2F1 transcripts during early infection." (PMID 26908453, 2016). "The inhibitory effect of the N-terminal domain of EBNA3C on E2F1 mediated transcriptional activity led us to further investigate the basal expression levels of E2F1 in primary infection model systems." (PMID 26908453, 2016).